MEF2C (myocyte enhancer factor 2C)
Description:
Transcription activator which binds specifically to the MEF2 element present in the regulatory regions of many muscle-specific genes. Controls cardiac morphogenesis and myogenesis, and is also involved in vascular development. Enhances transcriptional activation mediated by SOX18. Plays an essential role in hippocampal-dependent learning and memory by suppressing the number of excitatory synapses and thus regulating basal and evoked synaptic transmission. Crucial for normal neuronal development, distribution, and electrical activity in the neocortex. Necessary for proper development of megakaryocytes and platelets and for bone marrow B-lymphopoiesis. Required for B-cell survival and proliferation in response to BCR stimulation, efficient IgG1 antibody responses to T-cell-dependent antigens and for normal induction of germinal center B-cells. May also be involved in neurogenesis and in the development of cortical architecture (By similarity). Isoforms that lack the repressor domain are more active than isoform 1.
Synonyms: C5DELq14.3; DEL5q14.3; NEDHSIL
Tractability: PROTAC: UniProt records ubiquitination sites on it; ubiquitination databases record sites on it; its protein half-life has been measured.
Gene: Protein-coding gene on chromosome 5 (88,717,117 to 88,904,257, reverse strand). Ensembl gene ENSG00000081189.
Subcellular location: Nucleus; Cytoplasm, sarcoplasm
Subcellular location (Human Protein Atlas): Nucleoplasm; Vesicles
Pathways (Reactome):
Developmental Biology: Cardiogenesis; Myogenesis
Cellular responses to stimuli: Heme signaling
Circadian clock: Expression of BMAL (ARNTL), CLOCK, and NPAS2
Organelle biogenesis and maintenance: Transcriptional activation of mitochondrial biogenesis
Signal Transduction: ERK/MAPK targets
Gene Ontology:
Molecular function: DNA-binding transcription activator activity, RNA polymerase II-specific; DNA-binding transcription factor activity; DNA-binding transcription factor activity, RNA polymerase II-specific; DNA-binding transcription factor binding; minor groove of adenine-thymine-rich DNA binding; protein binding; protein heterodimerization activity; RNA polymerase II transcription regulatory region sequence-specific DNA binding; RNA polymerase II-specific DNA-binding transcription factor binding; sequence-specific double-stranded DNA binding; histone deacetylase binding; RNA polymerase II cis-regulatory region sequence-specific DNA binding; transcription cis-regulatory region binding; DNA binding; protein dimerization activity
Biological process: cellular response to parathyroid hormone stimulus; cellular response to transforming growth factor beta stimulus; heart development; MAPK cascade; myotube differentiation; negative regulation of blood vessel endothelial cell migration; negative regulation of ossification; negative regulation of transcription by RNA polymerase II; negative regulation of vascular associated smooth muscle cell migration; negative regulation of vascular associated smooth muscle cell proliferation; negative regulation of vascular endothelial cell proliferation; neuron differentiation; positive regulation of cardiac muscle cell differentiation; positive regulation of DNA-templated transcription; positive regulation of gene expression; positive regulation of myoblast differentiation; positive regulation of skeletal muscle cell differentiation; positive regulation of skeletal muscle tissue development; positive regulation of transcription by RNA polymerase II; regulation of DNA-templated transcription; AMPA selective glutamate receptor signaling pathway; B cell homeostasis; B cell proliferation; B cell receptor signaling pathway; blood vessel development; and 58 more
Cellular component: cytoplasm; nuclear speck; nucleus; protein-containing complex; chromatin; cytosol; nucleoplasm; postsynapse; sarcoplasm
Genetic constraint (gnomAD): Loss-of-function variants: 4 observed, 43.24 expected, observed/expected ratio (o/e) 0.0925, 90% interval 0.045 to 0.21. The upper end of that interval is the gene's LOEUF score, 0.21, which puts it in group 1 of 6, group 1 being the genes least tolerant of losing a copy. Missense variants: 269 observed, 590.3 expected, observed/expected ratio (o/e) 0.46, 90% interval 0.41 to 0.5. Synonymous variants: 181 observed, 225.77 expected, observed/expected ratio (o/e) 0.8, 90% interval 0.71 to 0.91.
Gene-disease validity (ClinGen):
ClinGen rates the evidence that MEF2C causes each of these diseases.
complex neurodevelopmental disorder (autosomal dominant): Definitive. A disorder that involves more than one phenotype associated with the central nervous system, including but not limited to intellectual disability, autism, and seizures (epilepsy).
Homologues: Orthologues: macaque MEF2C (100% identical), chimpanzee MEF2C (95% identical), dog MEF2C (95% identical), pig MEF2C (95% identical), guinea pig MEF2C (94% identical), rabbit MEF2C (94% identical), mouse Mef2c (94% identical), rat Mef2c (92% identical), tropical clawed frog mef2c (90% identical), zebrafish mef2cb (81% identical), zebrafish mef2ca (79% identical). Paralogues in human: MEF2A (63% identical), MEF2D (57% identical), MEF2B (33% identical), SRF (18% identical).
Diseases named in the same sentence as MEF2C in open-access papers:
MEF2C is named in the same sentence as 242 diseases in open-access papers, as found by Europe PMC text mining. Sharing a sentence is not in itself a finding about the gene and the disease. The quoted sentences say what the papers report.
cardiac hypertrophy (35 papers, 2009 to 2025). "ChIP-seq further unveiled EBF1 occupancy on promoters of genes linked to cardiac hypertrophy, including MEF2C and NPPA/NPPB." (PMID 39239522, 2024). "For example, loss of function of HDAC5 or HDAC9 has been associated with binding and silencing myocyte enhancer factor 2C (MEF2C), leading to a higher susceptibility to cardiac hypertrophy and cardiac failure." (PMID 33809061, 2021). "The involvement of HATs and HDACs in cardiac hypertrophy and fibrosis is explained by their ability to regulate histone acetylation at the promoter region of Gata4 and Mef2c and to associate with these transcription factors." (PMID 31936461, 2020). "On the other hand, H2S activates MEF2C and initiates miR-133a, which results in the prevention of cardiac hypertrophy." (PMID 39334911, 2024). "WWP1 also promotes atypical K27-linked ubiquitin multichain assembly on DVL2 and exacerbates cardiac hypertrophy via the DVL2/CaMKII/HDAC4/MEF2C pathway." (PMID 38674024, 2024). "Myocyte enhancer factor 2C activity is essential for pathological myocardial hypertrophy, and inhibition of MEF2C has a protective effect on chondrocytes hypertrophy." (PMID 36408215, 2022). "MEF2C has been emphasized as a signal-responsive mediator of the cardiac transcriptional program and plays a key role in the development of cardiac hypertrophy." (PMID 33817315, 2021). "Knockdown of TUG1 rescued Ang II-induced hypertrophy in cardiomyocytes at least partly through targeting the miR-497/MEF2C axis, highlighting a novel promising therapeutic target for cardiac hypertrophy treatment." (PMID 33817315, 2021). "To provide further mechanistic insight into the link between miR-497 and MEF2C in cardiac hypertrophy, we cotransfected miR-497 mimic and pcDNA-MEF2C into cardiomyocytes before Ang II induction." (PMID 33817315, 2021). "Mef2c acts as a nodal point for stress-response andremodelling programs during cardiac hypertrophy and fibre-type switching muscles." (PMID 32779443, 2020). "The DNA-binding activity of Mef2c increases in the pressure overload-induced cardiac hypertrophy in mice." (PMID 33193725, 2020). "IGF-1 is known regulator of Myocyte enhance factor 2C (MEF2C), which plays an active role in diabetes-provoked cardiac hypertrophy." (PMID 30013975, 2018). "On other hand, miR-133a is also a direct target of myocyte enhancer factor-2C (MEF-2C) which is a key transcription factor for myocardial hypertrophy and fibrosis through activation of p300 gene." (PMID 29566757, 2018). "Our current study has provided several lines of evidence to support the notion that miR-214-3p inhibits cardiac hypertrophy through targeting MEF2C." (PMID 27796324, 2016). "To elaborate on the DNA methylation array results, we selected several DMRs at different gene loci related to cardiac hypertrophy including Mef2c, Tnnt2, Myh6, Myh7, and Gata4 and body weight Ins2 for bisulfite sequencing." (PMID 24475304, 2014). "In the present study, ANP, MEF2A and MEF2C (molecular markers of cardiac hypertrophy) gene expressions were significantly higher in the diabetic group compared with the controls." (PMID 23497378, 2013). "In particular the higher transcription of the cardiac transcription factors Nkx2.5 and Mef2C can be regarded as markers for cardiac hypertrophy/growth." (PMID 22577878, 2012). "It has been demonstrated in mice that over-expression of Mef2C is sufficient to induce cardiac hypertrophy." (PMID 22577878, 2012). "Overall, these data highlight the potential of MEF2C in the pathogenesis of cardiac hypertrophy and remodeling, and provide insights into novel therapeutic targets to heart disease." (PMID 20041152, 2009). "A study found that REV-ERBα, upon co-localization with MEF2a and MEF2c, could specifically inhibit MEF2a/MEF2c-driven cardiac hypertrophy and the aberrant activation of gene programs in HF, thereby playing a critical role in preventing ventricular remodeling." (PMID 40255337, 2025).
cardiac hypertrophy (continued). "MEF2a and MEF2c are key regulators of the cardiac hypertrophy gene program." (PMID 40255337, 2025). "Therefore, the diminished binding of EBF1 to the MEF2C promoter resulted in heightened MEF2C transcription within cardiomyocytes, thereby contributing to the development of cardiac hypertrophy." (PMID 39239522, 2024). "Our previous research found that E3 ubiquitin ligase WWP1 can stabilize DVL2 by catalyzing K27-linked polyubiquitination, and DVL2 positively correlated with WWP1 hypertrophic heart and mediated the regulation of the CaMKII/HDAC4/MEF2C axis in cardiac hypertrophy by WWP1." (PMID 34733849, 2021). "In this study, the upregulation of nuclear receptor corepressor 1 (NCOR1), a transcription regulator known to recruit histone deacetylases and established repressor of cardiac hypertrophy, was proposed to account for the diminution of MEF2c in decompensated RV." (PMID 34208388, 2021). "Cardiac overexpression of Mef2a and Mef2c also induced cardiac hypertrophy and dilation." (PMID 34208388, 2021). "In addition, the calcineurin-MEF2C pathway was demonstrated to participate in cardiac hypertrophy induced by endoplasmic reticulum stress in neonatal rat cardiomyocytes." (PMID 33817315, 2021). "Mef2c also has a central involvement in cardiac hypertrophy and remodeling after heart failure." (PMID 33193725, 2020). "Also, they detected a significant correlation of the gene expression of TRPC1 and MEF2c (myocyte enhancer factor 2c), considered a key transcription factor for cardiac hypertrophy." (PMID 31936700, 2020). "MEF2a, MEF2c, and MEF2d have been demonstrated to play vital roles in cardiac hypertrophy." (PMID 31532577, 2019). "Furthermore, MEF2a, MEF2c, and MEF2d are well characterized for their crucial roles in cardiac hypertrophy, and MEF2b has been implicated to play a role in cardiac development." (PMID 31532577, 2019). "Taken together, our results revealed that MEF2C is a novel target of miR-214-3p, and attenuation of miR-214-3p expression may contribute to MEF2Cexpressionin cardiac hypertrophy." (PMID 27796324, 2016). "Therefore, we focused on deciphering and discussing their regulatory roles in cardiac hypertrophy in the following sections and 5 focused NFAT associated genes (PLCE1, PPP3R1, PPP3CB, CAMK1, MEF2C) were studies for experimental validation." (PMID 27907007, 2016). "Our data suggest that MEF2C is a novel target of miR-214-3p in myocardial hypertrophy, and enhancement of miR-214-3p expression may be protective against myocardial hypertrophy." (PMID 27796324, 2016). "Conversely, the activation of this pathway might be involved, together with changes in mitochondrial biogenesis and function, to the detrimental effects of MEF2C activation in cardiac hypertrophy." (PMID 20041152, 2009). "Nevertheless, the role of each specific MEF2 member, such as MEF2A or MEF2C, in cardiac hypertrophy remains unclear mainly because of the lethal cardiac phenotypes resulting from genetic deletions of these members." (PMID 20041152, 2009). "Likewise, MEF2c is known to be involved in the development of cardiac hypertrophy, which could be verified by our gene expression results." (PMID 31717562, 2019). "Mef2c expression and MEF2C protein levels are increased in the myocardium of mice with angiotensin II induced cardiac hypertrophy, and MEF2C silencing by siRNA attenuates ventricular hypertrophy in an angiotensin II and aortic banding model of cardiac hypertrophy." (PMID 30984767, 2019). "This resulted in the identification of KLF-4 interactions with genes like GATA4, MEF2C, TBX5, NKX2.5, and SRF, all of which are known regulators of cardiac hypertrophy and pro-hypertrophic pathways." (PMID 38672763, 2024). "Since MEF2c is connected to GATA4 and Isl-1, other groups have documented the upregulation in gene expression in connection with cardiac hypertrophy." (PMID 31717562, 2019).
cardiac hypertrophy (continued). "HHcy induces cardiac hypertrophy by facilitating MEF2C-HDAC1 complex formation, inactivating MEF2C, and inhibiting miR-133a in cardiomyocytes." (PMID 30298008, 2018). "The full length of mef2c decreased in MHC-CELF transgenic mice, leading to cardiac hypertrophy." (PMID 28077597, 2017). "Notably, the expression patterns of PPP3CB, PPP3R1, PLCE1, MEF2C and CAMK1 in the “NFAT in cardiac hypertrophy” pathway played a significant role in the activation of hypertrophy of atrial myocytes in MR patients compared to normal subjects." (PMID 27907007, 2016). "At the molecular level, the mRNA expression of markers of cardiac hypertrophy was significantly higher in the LV from sik2+/+ mice drinking 1% saline vs. normal salt (β-MHC = A.U.: 0.53±0.05 vs. 1.23±0.26, p = 0.025; MEF2C = A.U.: 0.38±0.02 vs. 0.62±0.01, p = 0.045), but not in sik2−/− mice." (PMID 24752134, 2014).
epilepsy (32 papers, 2013 to 2025). A brain disorder characterized by episodes of abnormally increased neuronal discharge resulting in transient episodes of sensory or motor neurological dysfunction, or psychic dysfunction. "Research has linked MEF2C deficiency syndrome to moderate to severe intellectual disability, epilepsy, and language impairment, which was validated in animal models." (PMID 40608414, 2025). "From the evidence chains we see that Ibudilast, through its association with modulating both the cAMP and cGMP pathways, is linked to FXS through the proteins AKT1 and MEF2C, and their association with epilepsy." (PMID 38977662, 2024). "MEF2C haploinsufficiency has been associated with ASD as well as epilepsy and intellectual disability." (PMID 38355786, 2024). "Mutations or dysfunctions in MEF2C have been reported to cause, for example, autism-like symptoms, intellectual deficits, and epilepsy." (PMID 38827438, 2024). "More recent work confirms the further identification of SIK1 mutations and resulting alterations MEF2C regulation in pediatric epilepsies." (PMID 36731029, 2023). "This mutation dysregulated cellular transcriptome and metabolome, specifically MEF2C-dependnet genes and certain epilepsy causing genes." (PMID 36834528, 2023). "Because of the important effects of MEF2C on synapses, MEF2C gene mutations or dysfunctions will lead to a series of syndromes, including intellectual deficiency, epilepsy and autism-like symptoms." (PMID 34991657, 2022). "Certainly, patients with complete deletion of MEF2C have an increased risk for developing epilepsy, relative to those with partial deletion." (PMID 34991657, 2022). "It is primarily expressed in the brain and haploinsufficiency of MEF2C is associated with severe cognitive impairment, stereotypic movements, epilepsy and cerebral malformation." (PMID 33594131, 2021). "ASD patients carrying rare functional variants of CNTNAP2 or MEF2C were more likely to have epilepsy/tics and require monitoring of these comorbidities." (PMID 30763456, 2019). "Consecutively, intragenic deletions/insertions and point mutations of MEF2C were discovered in patients with neurodevelopmental disorders, including intellectual disability and epilepsy." (PMID 30376817, 2018). "Its expression correlates with that of MEF2C (probe 209200_AT)- a gene linked with severe intellectual disability (ID), stereotypic movements and epilepsy." (PMID 24699272, 2014). "Moreover, subjects with partial MEF2C deletion have a lower risk for developing epilepsy compared to those with complete loss of MEF2C function." (PMID 36834528, 2023). "Etiopathogenic factors in other conditions are also associated with MEF2C in epilepsy." (PMID 34991657, 2022). "We are the first to show that rare functional variants of CNTNAP2 and MEF2C could significantly increase the risk of comorbid epilepsy/tics in nonsyndromic ASD patients, which should have a significant impact on ASD patient management." (PMID 30763456, 2019). "Variants in CNTNAP2 and MEF2C were correlated with epilepsy/tics in cases." (PMID 30763456, 2019). "The MEF2C target gene expression in epilepsy may also be affected by other pathogenic mutations." (PMID 36834528, 2023). "Interestingly, mutations in MEF2C gene have been identified in patients with epilepsy." (PMID 25078263, 2015). "As a MADS Box TF crucial for neurodevelopment, MEF2C is involved in various neuropsychiatric diseases, including autism spectrum disorder, epilepsy, and schizophrenia." (PMID 39350345, 2024).